BCL2 (BCL2 apoptosis regulator)
Diseases named in the same sentence as BCL2 in open-access papers (continued):
Sharing a sentence is not in itself a finding about the gene and the disease.
breast carcinoma (continued). "It has been reported that the inhibition of S6K1 enhances the cytotoxicity of breast cancer cells via Bcl-2/ Bcl-xL inhibition." (PMID 35955892, 2022). "Exosomal lncRNA-SNHG14 (lncRNA-small nucleolar RNA host gene 14) in breast cancer promotes trastuzumab resistance in HER2+ patients by targeting the apoptosis regulator Bcl-2 (Bcl-2)/apoptosis regulator BAX (Bax) signaling pathway." (PMID 36117723, 2022). "The previous reports on the phytochemical-mediated increase in caspase-3/8 and BAX and the decrease in the Bcl2-level-induced apoptosis in breast cancer cells corroborates our findings." (PMID 36676955, 2022). "Bcl-2 was a significant predictor in epithelial ovarian cancer patients (0.838) and breast cancer patients (AUC = 0.841)." (PMID 36699321, 2022). "In particular, Bcl-2 has been identified as an important prognostic marker across all breast cancer subtypes." (PMID 35053443, 2022). "This study uses a multi-omics approach to understand the global gene expression and metabolite changes induced by Disarib, a novel Bcl2-specific inhibitor in the Ehrlich adenocarcinoma (EAC) breast cancer mouse model." (PMID 35885991, 2022). "Cytotoxicity and effect of 10d and 10l on apoptotic markers Bax and Bcl-2 in breast cancer cell line (MCF-7) and lung cancer cell line (A549)." (PMID 35631321, 2022). "Icariin, as the main component of Icarii, inhibits the proliferation of breast cancer cells and induces apoptosis in concentration and time-dependent, and upregulates the ratio of Bax/Bcl-2 and reactive oxygen species through mitochondrial pathways." (PMID 36686745, 2022). "Apoptotic and cytotoxic effects were shown by nano-prototypes on MCF7 and MDA-MB-231 breast cancer cell lines.Expression levels of Cas-3 and Bax were up-regulated, while the expression levels of BCL-2, NF-ĸB, and PI3k were down-regulated." (PMID 36235486, 2022). "Combination studies also reveal stattic is synergistic with SOC therapeutic, doxorubicin, and suppresses anti-apoptotic genes, Bcl-2 and Bcl-xL, to promote breast cancer cell apoptosis." (PMID 35371975, 2022). "As expected, the results revealed that BCL2 expression was lower in breast cancer tissues than in normal tissues (p < 0.001)." (PMID 35251139, 2022). "In a recent paper, in patients with ER positive breast cancer who received adjuvant endocrine therapy, Bcl-2 predicted favourable outcomes, although its presence has been associated with worse prognosis." (PMID 35992829, 2022). "Paclitaxel induced 60% increase in apoptosis and G2/M phase cell-cycle arrest in Canine mammary cancer cells by down regulating Bcl-2 and up regulating Bax." (PMID 35422844, 2022). "Regarding autophagy induction for breast cancer therapy, a promising approach is to target the formation of Bcl-2/Bcl-XL-Beclin1 complexes by using selective Bcl-2 inhibitors." (PMID 34207792, 2021). "Through overexpression of Bcl-xL, ABT-199 showed pre-clinical trial activity in breast cancer cells by investigation of the promise of ABT-199 as a Bcl-2 inhibitor." (PMID 34638779, 2021). "The role of Bcl-2 depletion on ACD induction was previously demonstrated in breast cancer cell lines." (PMID 33805467, 2021).
breast carcinoma (continued). "After being purified and characterized, GSF3 was found to inhibit MCF-7 breast cancer cell growth via the decreasing of Bcl-2 mRNA expression levels but the increasing of pro-(Bax)/anti-apoptotic (Bcl-2) mRNA expression ratios in the treated cells." (PMID 33807287, 2021). "In breast cancer cells, overexpression of Bcl-2 has been correlated to the formation of polyploid cells, which confer MDR properties to cancer cells." (PMID 34142021, 2021). "Matrine upregulates Bax and downregulates Bcl-2 to inhibit proliferation and increase apoptosis of breast cancer cells and further downregulates the canonical pathway to suppress human breast cancer stem-like cells." (PMID 34899291, 2021). "In the case of breast cancer cells, Bcl-2 is down-regulated by progesterone, which has been confirmed in numerous studies." (PMID 34683909, 2021). "GSF3, which is a novel polysaccharide isolated from guava (P. guajava L.)seeds, has been characterized and found to inhibit MCF-7 breast cancer cell growth through increasing either the Bax/Bcl-2 ratio or Fas mRNA levels in the target cancer cells." (PMID 33807287, 2021). "Previous studies have investigated the prognostic roles of BCL1 and BCL2 in various human cancers including breast cancer." (PMID 34099764, 2021). "Our study supports a theory that lncRNA APOC1P1-3 can promote development of breast cancer metastasis via anoikis resistance by specifically binding to miRNA-188-3p to block the inhibition of Bcl-2." (PMID 33902604, 2021). "Kaempferol has been reported to induce apoptosis in breast cancer cell lines in vitro, through downregulation of Bcl-2 and cleavage of PARP, similarly to the carob extracts." (PMID 34443605, 2021). "The expression of RBM genes (RBMX, RBM3, and RBM10) on the X chromosome, as well as the expression of apoptosis-related genes, namely Bcl-2 and Bax, was detected by differential RT-PCR in 122 cases of breast cancer." (PMID 33718153, 2021). "Here, we also showed an increased expression of BCL-2 upon S3 treatment in MCF7 breast cancer cells." (PMID 33498665, 2021). "Recently, the BCL-2 inhibitor venetoclax exhibited excellent efficacy when combined with endocrine therapy for estrogen receptor-positive breast cancers and entered testing for the treatment of HER2-positive breast cancers overall and TNBCs in particular." (PMID 34680527, 2021). "From our former observations, we noted that AS apoptotic induction is correlated with Bcl-2 down-regulation and Bax up-regulation in the cell lines of human breast cancer." (PMID 34031264, 2021). "In breast cancer cells, fraxetin inhibits cellular proliferation, induces mitochondrial-dependent apoptosis by upregulating Bax expression and downregulating Bcl-2 expression." (PMID 34320467, 2021). "High Bcl-2 levels are detected in an estimated 32–86% of breast carcinomas, and the overexpression of Bcl-2 can interfere with 99mTc-sestamibi uptake." (PMID 34679544, 2021). "Overexpression of the anti-apoptotic protein BCL-2 is frequently observed in multiple malignancies, including about 85% of patients with estrogen receptor positive (ER+) breast cancer." (PMID 34063475, 2021). "In recent studies, BCL2 inhibitors have been suggested as a possible therapeutic approach to breast cancer, both due to their apoptosis-enabling effect and their potential synergistic effect with tamoxifen as an ER inhibitor." (PMID 34441794, 2021).
breast carcinoma (continued). "Intracellular staining of BCL-2 protein by flow cytometry revealed a significant reduction in BCL-2 levels in breast cancer cells likewise upon treatment with 200 μg/mL of siBCL-2 NKExos." (PMID 34063475, 2021). "Upregulation of Bim, which can bind to Bcl-2 and Bcl-XL via its BH3 domain, thereby sequestering Bcl-2 from the pro-apoptotic Bax and Bad, and initiating the apoptotic cascade, has been seen in breast cancer cells treated by SZ-685C." (PMID 34440090, 2021). "Ori exerts antitumor activity through the regulation of the expressions of ERK, Bax/Bcl-2, and NF-κB in various cancer diseases, such as leukemia, breast cancer, gastric cancer, and lung cancer." (PMID 34566976, 2021). "It induces breast cancer cell apoptosis through the regulation of Bcl-2/Bax/caspase 3 signaling, or the CXCR3-B/CXCL4 signals." (PMID 34122605, 2021). "Our results show high expression of bcl-2 suggesting an important role of apoptosis in Ghanaian breast cancer cases." (PMID 34188682, 2021). "The anticancer effect of siRNA against anti-apoptotic genes, namely, Mcl-1, Bcl-2, and survivin, were first screened in breast cancer cell line MCF-7 and MDA-MB-231." (PMID 33919902, 2021). "Biological characterisation of over 14,000 primary breast cancers has shown an increase in BCL-2 expression with age." (PMID 33226492, 2021). "In breast cancer, BCL-2 likewise plays an important role in preventing apoptosis and upregulated expression correlates with estrogen receptor (ER) positivity." (PMID 34063475, 2021). "In particular, it has been reported that tamoxifen-treated ER+ breast cancers often present high BCL-2 and BCL-xL expression, and that tumors harboring elevated MCL-1 protein expression exert poorer prognosis." (PMID 34359829, 2021). "Overexpression of the Bcl-2 protein has been reported in prostate cancer, breast cancer, B-cell lymphomas, and colorectal cancer." (PMID 34768743, 2021). "Overexpression of Bcl-2 makes cells resistant to apoptosis, a phenomenon found in breast cancer and many other cancers." (PMID 34567111, 2021). "Preferentially, the expression of CD34 and Bcl-2 were proved to be the predictors of neoadjuvant chemotherapy in urothelial bladder cancer and breast cancer." (PMID 33392721, 2021). "When PrPC is upregulated, Bcl-2/Bax ratio increases, resulting in anti-apoptosis in breast carcinoma MCF-7 cells." (PMID 34595121, 2021). "In that study, ERRβ significantly inhibited E2-stimulated proliferation and expression of bcl-2 in MCF-7 breast cancer cells." (PMID 34089362, 2021). "Several investigations revealed ATRA and its derivative provoke breast cancer cell death by decreasing Bcl-2 activity and increasing Bax and caspase activities." (PMID 34579037, 2021). "This study investigated the prognostic roles of BCL1 and BCL2 expression in breast cancer using tissue microarrays from 393 operable primary breast cancer patients." (PMID 34099764, 2021). "Of those, BCL2, which is down-regulated in radioresistant breast cancer cells and tissue, can suppress apoptosis by inhibiting the activity of caspases indispensable for apoptosis, such as caspase-3 (CASP3)." (PMID 33898418, 2021). "We found that caspase-3/8/9 and Bax expressions were elevated in breast cancer tissues, while Bcl-2 expression was decreased in breast cancer tissues." (PMID 33987194, 2021). "To this end, we developed a therapeutic strategy to target overexpressed BCL-2 in ER+ breast cancer cells with exosomes loaded with small interfering RNA (siRNA) targeting BCL-2 (siBCL-2) derived from lentivirally modified NK cells." (PMID 34063475, 2021). "Our results show high expression of bcl-2 (protein) suggesting an important role of apoptosis in Ghanaian breast cancer cases." (PMID 34188682, 2021). "Using doxorubicin as a control, the most active caspase activators 8e and 8g were further investigated for their impact on Bax and Bcl-2 levels in the MCF-7 breast cancer cell line." (PMID 34833890, 2021).
breast carcinoma (continued). "Higher levels of BCL2 expression in breast tumors have been shown to be an independent prognostic factor for improved survival from breast cancer." (PMID 34068181, 2021). "We investigated the prognostic influences of BCL1 and BCL2 expression on disease-free survival in breast cancer patients." (PMID 34099764, 2021). "The MCF-7 breast cancer cell line showed that both pollutants increased the expression of ER receptor target genes, including the progesterone receptor, bcl-2, and trefoil factor." (PMID 34199666, 2021). "Inhibiting the expression of miRNA‐21‐5p can reduce the proliferation of breast cancer cell lines and promote apoptosis of breast cancer cells by indirectly downregulating the antiapoptotic factor Bcl‐2." (PMID 34254453, 2021). "This study investigated the prognostic impacts of BCL1 and BCL2 expression in breast cancer by utilizing tissue microarray data of breast cancer patients." (PMID 34099764, 2021). "Together, our prototypical results for BCL-2 in breast cancer provide proof of concept for a novel strategy to utilize NKExos as a natural delivery vector for siRNA targeting of oncogenes." (PMID 34063475, 2021). "Although BCL1 and BCL2 were expected to be adverse prognostic indicators in breast cancer, the results have been largely inconsistent." (PMID 34099764, 2021). "Here, we conceptualized a novel treatment strategy by targeting ER+ breast cancer with NK cell-derived exosomes used as a carrier for BCL-2 targeted siRNAs." (PMID 34063475, 2021). "Specific targeting of BCL-2 by siRNA in various malignancies including breast cancer demonstrated growth inhibition, apoptosis induction, and enhanced susceptibility to chemotherapy in vitro and preliminary in vivo studies." (PMID 34063475, 2021). "Although most cancer cases are characterized by the increased level of Bcl-2, some authors reported on low expression of Bcl-2 in breast cancer and Waldenström macroglobulinemia." (PMID 34337053, 2021). "Bcl-2 itself is a transcriptional target of ER and is upregulated in up to 90% of ER+ breast cancers." (PMID 34804982, 2021). "BCL1 and BCL2 expression statuses were assessed by immunohistochemistry using tissue microarrays from 393 breast cancer patients." (PMID 34099764, 2021). "This led us to reason that strategies for specific targeting of cancer cells would constitute promising approaches to implement BCL-2 inhibition in ER+ breast cancer." (PMID 34063475, 2021). "This study investigates the prognostic effects of BCL1 and BCL2 expression in breast cancer by analyzing tissue microarray data of primary breast cancers." (PMID 34099764, 2021). "For example, ERβ agonists decreased Bcl-2 level and thus activated autophagy in hormone-resistant breast cancer cells." (PMID 34714484, 2021). "In summary, lncRNA APOC1P1-3 can promote the anoikis resistance of breast cancer cells and specifically bind to miRNA-188-3p acting as a “sponge” to block the Bcl-2 inhibition." (PMID 33902604, 2021). "Suppression of ITGAV inhibited cell growth, invasion, and self-renewal of breast cancer by altering BCL2 and PXN levels." (PMID 34249086, 2021). "In fact, in some cases, BCL-2 expression correlates with improved clinical outcome, for example in patients with Estrogen Receptor (ER)- and Progesterone Receptor (PR)-positive breast cancer who received adjuvant endocrine therapy." (PMID 33799592, 2021). "miR-34a inhibits proliferation and migration of breast cancer through down-regulation of Bcl-2 and SIRT140." (PMID 34702958, 2021). "The present case-control study was aimed to examine the association of BCL-2 (-938C> A), BAX (-248G > A), and HER2 (I655V i.e. A > G) polymorphisms with breast cancer risk in Indian population." (PMID 33708254, 2021).
breast carcinoma (continued). "β-carotene can suppress the expression of Bcl-2 and NF-κB and activate the family of cysteine-aspartic proteases called caspase 3, inducing apoptosis of breast cancer cells." (PMID 34579037, 2021). "Downregulation of PrPC sensitizes adriamycin-resistant human breast cancer cells to TRAIL-induced apoptosis by increasing Bax/Bcl-2 ratio." (PMID 34595121, 2021). "Effect of QBS 11c and 13b on the expression levels of Bax, Bcl-2 and active Caspase-3 in breast cancer MCF-7 cells." (PMID 34681794, 2021). "Increasing studies have demonstrated that BCL2 is involved in carcinogenesis of multiple types of cancer, including breast cancer." (PMID 34828282, 2021). "Effect of QBS 11c and 13b on the expression levels of Bax, Bcl-2 and active Caspase-3 in breast cancer MDA-MB-231 cells." (PMID 34681794, 2021). "PDX-BRB4 with its progressed subline is a preclinical model mirroring the clinical paradox of high level-BCL2 as a good prognostic factor in breast cancer." (PMID 33452364, 2021). "In human breast cancer cells, delphinidin treatment inhibited cell proliferation by blocking the Akt signaling pathway and inducing apoptosis by increasing Bcl-2 expression along with increasing Bax expression in a dose-dependent manner." (PMID 34768743, 2021). "BCL2 is also believed to have an adverse influence on breast cancer survival, but most previous studies have reported a favorable prognostic effect." (PMID 34099764, 2021). "For example, BCL2 over-expression results in paclitaxel resistance in melanoma and breast cancer cells." (PMID 34385422, 2021). "As was shown in a study on women with breast cancer, only one of 17 cases demonstrated elevated Bcl-2 in metastases." (PMID 34683909, 2021). "The NK cell line NK92MI was lentivirally transduced to express and load BCL-2 siRNAs (siBCL-2) into exosomes (NKExos) and then evaluated for its potential to treat ER+ breast cancer." (PMID 34063475, 2021). "The importance of Bcl-2 as a mediator of SCAP was also reported during doxorubicin-induced senescence in breast cancer cells." (PMID 34298797, 2021). "Several reports described the regulation of Bcl-2 by miR-148a and identified it as one of its target proteins in colorectal cancer, pancreatic cancer and breast cancer." (PMID 34181356, 2021). "Further studies are required to validate the usefulness of BCL2 expression as a prognostic marker in breast cancer." (PMID 34099764, 2021). "After performing correlation analysis, expression analysis and survival analysis, BCL2 was identified as the most potential downstream target gene of MUC14-miR-137/miR-429 axis in breast cancer." (PMID 34828282, 2021). "In breast cancer cells, activation of STAT3 via the IL-6/JAK2 cascade causes suppression of Bax/Bcl-2-associated caspase-dependent apoptosis." (PMID 34488773, 2021). "To confirm the apoptotic effect of Statmp-151 on breast cancer cells, we determined the expression of Bcl-2, Bax and Cleaved caspase-3 (CC3) in MDA-MB-231 and 4T1 cells after treatment with Statmp-151 for 24 h." (PMID 33967793, 2021). "BCL-2 dependencies have been described with the context of HER2-/ER+ breast cancers, which are enriched for BCL-2 expression." (PMID 33951110, 2021).